BRCA1 (BRCA1 DNA repair associated)
Diseases named in the same sentence as BRCA1 in open-access papers (continued):
Sharing a sentence is not in itself a finding about the gene and the disease.
tumor (continued). "Eighteenpercent of undifferentiated tumors (tumor grade 3, N = 17) and 16% of tumors from patients with any residual disease(N = 15) were positive for BRCA1 DNA-methylation (P = 0.004, and P = 0.013; respectively)." (PMID 30111871, 2018). "Mutations in BRCA1 or BRCA2, homologous recombination deficiency (HRD), and platinum sensitivity were associated with tumor response." (PMID 29313279, 2018). "In contrast to mutations in BRCA1 and BRCA2, which are predisposing for both BC and OC, several risk genes appear to be tumour-site specific." (PMID 29368626, 2018). "Our data show that in normal mammary epithelial cells, LYN kinase activity is under the strict control of the c-KIT receptor, whereas in Brca1 mutant tumor cells, LYN functions independently of c-KIT." (PMID 30590041, 2018). "Pathogenic homozygous BRCA1 and BRCA2 mutations were later detected in tumor cells by next-generation sequencing." (PMID 29729664, 2018). "These experiments showed that survival of Brca1-mutant tumor cells decreased with each increment in cyclin B1 induced by successively higher concentrations of vinblastine." (PMID 30327455, 2018). "Here we present next generation sequencing (NGS) of tumour DNA from a cohort of OC patients treated with PLD monotherapy from a single centre in order to better interrogate the interaction between BRCA1/2 status and response to PLD." (PMID 29298688, 2018). "This combination of indel and rearrangement patterns showed a high degree of similarity to those seen in primary tumours with defects of other well-known HR components such as BRCA1 and BRCA215,17." (PMID 29717121, 2018). "BRCA1-associated tumours bear resemblance to TNBC and basal-like tumours, suggesting conserved biological mechanism of tumourigenesis for these tumour types." (PMID 30323900, 2018). "There was a similar trend for superior response rate to PLD in the BRCA1/2-mutant population following the exclusion of patients whose tumour harboured only rs1799950 (31.6%, 6 of 19 patients vs. 12.1%, 7 of 58 patients; Fisher’s exact test p = 0.075)." (PMID 29298688, 2018). "Tumor size was an independent indicator of poor prognosis of OS (P = 0.022) and BRCA1 expression predicted poor prognosis of RFS (P = 0.046)." (PMID 29784019, 2018). "BRCA1 is a tumor suppressor gene that is located on chromosome 17q21 involved in DNA error-free repair by homologous recombination." (PMID 30453575, 2018). "BRCA1 and BRCA2 (BRCA1/2) are human tumor suppressor genes which play a role in DNA damage repair and transcriptional regulation." (PMID 29861850, 2018). "In arm A, 57% and 43% of patients carried deleterious BRCA1 and BRCA2 mutations, respectively; 56% and 44% had triple-negative and HR+ disease; and 59% had more than two tumor sites (liver metastasis, 52%; CNS metastasis, 6%)." (PMID 30240327, 2018). "GFRA1-PBD demonstrated synthetic lethality with DDR deficiency, both in vitro in BRCA1-isogenic paired cells and in vivo in the CTG-0012 model, suggesting enhanced sensitivity of tumor cells to a GFRA1 ADC despite low receptor density." (PMID 29796165, 2018). "Understanding the biological consequences of BRCA1 interactions with its binding partners is important for elucidating its tissue-specific tumor suppression function." (PMID 29426838, 2018). "Of these, the expression of miR-29b-1-5p was significantly upregulated, consistent with our Brca1 knockout data and sequencing from the BRCA1 mutant tumours." (PMID 30323900, 2018).
tumor (continued). "Tumours arsing in Brca1 knockout mice share many morphological characteristics with their human counterparts including abnormal nuclei and high mitotic index." (PMID 30323900, 2018). "Increasing evidence has shown that BRCA1 is involved in the regulation of tumor chemotherapy resistance and proliferation." (PMID 30594239, 2018). "We also noted additional BRCA1 mutant tumour cell lines (MDAMB436, HCC1395) and a BRCA1 promoter hypermethylated tumour cell line HCC3814 to display PARPi sensitivity, as did a number of synovial sarcoma tumour cell lines (SYO1, CME, HS-SYII, ASKA)." (PMID 30006631, 2018). "It is well established that approximately 80% of all BRCA1/2– related tumours have a triple-negative phenotype." (PMID 29928469, 2018). "Many clinical testing laboratories have now adopted NGS technologies for routine screening including germline BRCA1/2 testing (Patton) and some diagnostics laboratories are beginning to apply this technology for tumor BRCA1/2 (tBRCA) screening." (PMID 29215764, 2018). "Since some literature evidences are still underlying the importance of using of tumor materials as starting sample for tBRCA1/2 profiling, we decided to progressively switch from BRCA1/2 germline to tumor analysis." (PMID 29731958, 2018). "It has been reported that the removal of the BRCA1/CtIP/ZBRK1 repressor complex on the ANG1 promotor causes high expression of ANG1 in tumor cells, and promotes tumor growth by accelerating angiogenesis." (PMID 29959560, 2018). "BARD1 BRCT performs tumor suppressor function by recruiting BRCA1 at DNA damage site via interactions with other DNA damage repair (DDR) proteins." (PMID 35548793, 2018). "A small fraction of intracellular BRCA2 binds physically with BRCA1, consistent with evidence that these tumor-suppressor proteins share at least certain biological functions during the cellular response to DNA damage." (PMID 29386125, 2018). "BRCA1 has a central role in DNA damage response and tumor suppression, but its function in craniofacial bone development is not known." (PMID 29718910, 2018). "Tumor BRCA1/2 testing is important also as possible further surrogate biomarker of response to immune check-point inhibitors." (PMID 29731958, 2018). "For 12 of the 21 BRCA1-methylated cases, sufficient material from pre-treatment tumor biopsies was available." (PMID 30266954, 2018). "Numerous oncogenes and tumor suppressors are directly regulated by PIN1, and here we show that PIN1 is an important contributor to LYN hyperactivation in BRCA1 mutant tumor cells." (PMID 30590041, 2018). "BRCA1 and BRCA2 are well-characterised tumour suppressor genes that when heterozygously mutated in the germ line, increase the risk substantially for several malignancies, including breast, ovarian, pancreatic and prostate cancer." (PMID 30428574, 2018). "Low Brca1 protein expression levels are frequently found in various transformed cells or tumour cells." (PMID 30296263, 2018). "Patients with gBRCAmt often had better anti-tumour responses than those with wild-type BRCA1/2 (BRCAwt) and patients with platinum-sensitive disease had better responses than women with platinum-resistant or refractory disease." (PMID 29464354, 2018). "To characterize the neoplastic eye abnormalities in Brca1-mutant mice, we performed histopathological analyses of these tumor tissues." (PMID 30652068, 2018). "Significantly higher RASSF1 methylation levels were observed in association with BRCA1/2 mutations, HER2 expression and high tumor grade." (PMID 29731982, 2018). "Known as a multifunctional protein, BRCA1 suppresses tumor formation via a transcriptional co-activator or co-repressor function." (PMID 29757984, 2018).
tumor (continued). "Eighteen of the 212 evaluable patients had BRCA1-methylated tumours, of which the tumours from 16 patients were BRCA wild type." (PMID 30353044, 2018). "The tumor suppressor BRCA1 was shown to reduce Top2α activity through its E3 ubiquitin ligase activity." (PMID 29915179, 2018). "Nevertheless, many platforms, chemistries or pipelines showed either general or specific pitfalls regarding germline BRCA1/2 testing: these issues can become even more critical when the analysis is directly performed on FFPE tumor samples." (PMID 29731958, 2018). "Elucidating the biological significance of these diverse BRCA1functions in a physiologically relevant tissue context is pivotal to a better understanding of the molecular basis of BRCA1 function as a tissue-specific tumor suppressor." (PMID 29426838, 2018). "Using mammary epithelial-specific knockout (KO) mouse models for Brca1 and Cobra1, we recently demonstrated genetic complementation between these two genes during normal mammary gland development and tumor suppression." (PMID 29426838, 2018). "One of the two chemo-naive PDX with homozygous BRCA1 promoter methylation (#62) responded to 300 mg kg−1 rucaparib, with tumor regressions observed in two of seven mice (median TTH 71 days vs. vehicle 18 days, p < 0.001, log-rank test, n = 7, 11)." (PMID 30266954, 2018). "LYN knockdown markedly impaired growth of mouse Brca1 tumor-derived cells in monolayer culture and in three-dimensional (3D) culture conditions on Matrigel." (PMID 30590041, 2018). "BRCA1 deficiency activates the PI3K/AKT pathway in immortalized fibroblasts and tumor cells by accumulating nuclear AKT." (PMID 29996906, 2018). "By contrast, the EXO1 knockout rearrangement signature was dominated by medium-to-long tandem duplications emulating the alternative cohort of genomically unstable (but BRCA1-intact) tumours." (PMID 29717121, 2018). "Consistent with the findings derived from E2-treated p18−/−;Brca1MGKO and p16−/−;Brca1MGKO tumors, we also found that BRCA1 mutant PDX tumor development was significantly enhanced by E2 treatment relative to that by placebo." (PMID 29996906, 2018). "Genomic studies suggest that a subset of OS, including OS tumour cell lines (TCLs), exhibit genomic loss of heterozygosity (LOH) patterns reminiscent of BRCA1 or BRCA2 mutant tumours." (PMID 30006631, 2018). "BAP1 has been shown to bind to the BRCA1 protein enhancing BRCA1-mediated tumor suppression, and is involved in various biological processes including DNA damage response, regulation of the cell cycle and cell growth." (PMID 30477459, 2018). "In the current study, we also observed a strong correlation between high BRCA1 expression and the basal cell nature of the tumor (positive for EGFR and/or CK5/6)." (PMID 28863181, 2017). "Additional PRINCe assessments detected a putative complex rearrangement affecting BRCA1 in a patient with mCRPC, along with clinically relevant copy-number alterations in advanced treatment-naïve patients with heavy tumor burden (see Supplementary Results)." (PMID 29163793, 2017). "Two cases of STICs and one case of occult carcinoma were found only within fallopian tubes, consistent with the fallopian tube being the origin for BRCA1 and BRCA2 mutation-associated tumours." (PMID 28285341, 2017).
tumor (continued). "Results from the ARIEL2 Part 1 trial indicate, that BRCA1/2 wild-type tumors that have a high percentage of tumor genomic LOH, show an improved response to rucaparib treatment." (PMID 29137324, 2017). "We determined that miR-125a-3p inhibited the expression of BRCA1, a well-known tumor suppressor with multiple interacting partners and diverse biological functions." (PMID 28827743, 2017). "Tumor suppressors including KiSS1, BRCA1, p16, MEG3 and PPAR-gamma are known to inhibit the tumor cell migration and invasion." (PMID 28584306, 2017). "Bound to BRCA1, BARD1 is an essential component of BRCA1’s tumor suppressor activity due to the E3 ubiquitin ligase activity of the BRCA1-BARD1 heterodimer." (PMID 28786985, 2017). "Among the tumor samples, 16/68 (23.5%) belonged to the BRCA1-pathogenic group (mutated BRCA1), 16/68 (23.5%) were from BRCA1-VUS group and 36/68 (53%) were BRCA1 WT." (PMID 27926510, 2017). "The promoter methylation status of 22 tumor suppressor genes as well as 11 CpG sites in BRCA1 promoter region was then examined." (PMID 28199384, 2017). "The 90 kDa protein was initially thought to reduce tumorigenesis through the deubiquitination of BRCA1, though it was later revealed that BAP1 can achieve its tumor suppressive role independently of BRCA1." (PMID 29166932, 2017). "By correlating the expression levels of BRCA1 with clinical and tumor characteristics we observed that a significant proportion of cases with high levels of BRCA1 expression (35.0%) had tumors at early stages (T1, N0 and M0)." (PMID 27926510, 2017). "In this respect, it is noteworthy that the cellularity of cells with methylated CpG dinucleotides in BRCA1 promoter regions of the TN-6 and TN-13 samples were variegated, while those in other specimens coincided with tumor cellularity." (PMID 28636652, 2017). "Locus-specific LOH, which can be determined from already existing DNA-based FFPE tumor testing pipelines remains a clinically promising and more cost-effective means of predicting therapy response in germline BRCA1 and BRCA2 carriers." (PMID 28831036, 2017). "In conclusion, the mutation spectra measured in our controlled genetic model are in good agreement with correlative observational data obtained from BRCA1/2-defective human tumours." (PMID 27452521, 2017). "In BRCA1-mutant tumors, the capability of DNA damage repair is decreased, which makes tumor cells sensitive to DNA-damaging drugs; however, high BRCA1 activity weakens the effect of these drugs." (PMID 28359295, 2017). "BRCA1/2 loss-of-function mutations were found in 55% (114/209) of tumors, were mutually exclusive, and demonstrated high concordance with Sanger-sequenced germline mutations in matched blood samples, confirming the accuracy (97%) of tumor BRCA1/2 NGS testing." (PMID 28525389, 2017). "Recent clinical trials have focused around platinum agents and PARP inhibitors (particularly in BRCA1 associated TNBC), androgen receptor antagonists (LAR TNBC) and immune checkpoint inhibitors (TNBCs with high levels of tumor infiltrating lymphocytes)." (PMID 29113326, 2017). "The evaluation of BRCA1 expression was performed by RT-qPCR for 68 tumor samples and 49 matched normal samples (54 samples were excluded due to poor RNA quality)." (PMID 27926510, 2017). "An interesting finding was the identification of BRCA1 hypermethylation in the normal adjacent tissue in one sample (PRM = 37% in the tumor tissue and 7% in the normal tissue)." (PMID 27926510, 2017).
tumor (continued). "In our study, carboplatin inhibits tumor cells through inducing DNA damage, and curcumin-induced decreases in BRCA1 and BRCA2 expression contribute to carboplatin’s cytotoxic effect." (PMID 29255221, 2017). "We found limited genetic concordance between primary and secondary tumor sites with private mutations in FLT4, MTOR, ITGA5, SETD2, PBRM1, and BRCA1 on progression." (PMID 29088767, 2017). "BRCA1-IRIS expression measured using real time RT/PCR in these patients’ tumor samples was correlated to tumor characteristics, such as to clinico-pathological features, therapeutic responses, and survival outcomes." (PMID 28499366, 2017). "ZNF350 is a transcriptional repressor that has been suggested as a tumor suppressor due to its close corporation with BRCA1 and KAP-1 to silence DNA damage response genes." (PMID 29291027, 2017). "In order to determine a potential role of BRCA1/2 protein expression as surrogate marker for BRCA1/2 inactivation, tumor specimens of a subgroup of 16 patients selected from our cohort were analyzed by immunohistochemistry." (PMID 28676659, 2017). "BRCA1 H-score decreased as tumor grade increased (15% and 20% less in grade 2 and 3 than grade 1, respectively, p = 0.009) and was 25% to 30% higher for luminal B than other molecular subtypes." (PMID 28863181, 2017). "Epigenetic silencing, which disrupts BRCA1 transcriptional activity, can also be decisive for tumor formation in sporadic BCs." (PMID 29029467, 2017). "Strikingly enough, the three sera transformed BRCA1-KO cells, as confirmed by tumor formation, following transplantation in NOD/SCID mice." (PMID 28854931, 2017). "The tumor suppressor BRCA1 is among the central components of the surveillance system and it recruits various DNA repair proteins to the sites of damage." (PMID 29029467, 2017). "All pathogenic germline mutations in BRCA1 (n = 31) and BRCA2 (n = 16), known prior to smMIP‐based targeted sequencing, were called by the NextSeq software in 47 tumor samples derived from 38 patients." (PMID 27767231, 2017). "BRCA1-null tumor cells, which are defective for HHR, require alternative pathways including NHEJ and base excision repair for SSBs to repair damaged DNA." (PMID 29158484, 2017). "Studies also support that BRCA1 exerts its tumor suppression function through its involvement in cell cycle checkpoint control." (PMID 28427168, 2017). "BRCA1 (also known as RNF53) is a tumor suppressor, which acts as E3 ubiquitin-protein ligase that mediates the formation of Lys-6-linked polyubiquitin chains." (PMID 28452926, 2017). "Wild-type BRCA1 patients show higher tumor expression levels of AGTR1 compared to patients with BRCA1 mutations." (PMID 28439256, 2017). "As such, a key question is why can the BRCAness profile be defined by comparing BRCA1/2-mutant familial tumor samples with sporadic samples?" (PMID 29146938, 2017). "Gene expression profile showed in all groups lower BRCA1 mRNA levels in tumor tissue compared to the adjacent breast tissue, thereby indicating the loss/decrease of gene function." (PMID 27926510, 2017). "The CtIP protein is commonly thought to function as a tumor suppressor, a view predicated in part on its interaction with BRCA1." (PMID 27058754, 2016). "To examine the relationship between these two transcripts in individual tumor specimens, we plotted the transcript abundances of BRCA1 versus ID4." (PMID 27077368, 2016). "Mutations in proteins essential for HR, such as the breast cancer early onset (BRCA1 & BRCA2) tumor suppressor genes, have been associated with increased risk of tumor development and enhanced sensitivity to chemotherapeutic agents." (PMID 28033382, 2016). "BRCA1-mutant tumours generally show a considerable molecular, histological and clinical heterogeneity." (PMID 27881737, 2016).